ZSCAN1 (zinc finger and SCAN domain containing 1)
Description:
May be involved in transcriptional regulation.
Synonyms: FLJ33779; ZNF915; MZF-1
Tractability: No criterion of Open Targets' tractability assessment is met for any kind of drug.
Gene: Protein-coding gene on chromosome 19 (58,034,025 to 58,054,631, forward strand). Ensembl gene ENSG00000152467.
Subcellular location: Nucleus
Subcellular location (Human Protein Atlas): Nucleoli; Nucleoplasm
Gene Ontology:
Molecular function: protein binding; sequence-specific double-stranded DNA binding; DNA-binding transcription factor activity, RNA polymerase II-specific; RNA polymerase II cis-regulatory region sequence-specific DNA binding
Biological process: regulation of transcription by RNA polymerase II
Cellular component: chromatin; nucleus
Genetic constraint (gnomAD): Loss-of-function variants: 22 observed, 23.19 expected, observed/expected ratio (o/e) 0.95, 90% interval 0.68 to 1.35. The upper end of that interval is the gene's LOEUF score, 1.35, which puts it in group 5 of 6, group 1 being the genes least tolerant of losing a copy. Missense variants: 560 observed, 539.06 expected, observed/expected ratio (o/e) 1.04, 90% interval 0.97 to 1.11. Synonymous variants: 229 observed, 232.26 expected, observed/expected ratio (o/e) 0.99, 90% interval 0.88 to 1.1.
Homologues: Orthologues: chimpanzee ZSCAN1 (99% identical), macaque ZSCAN1 (94% identical), dog ZSCAN1 (62% identical), Drosophila melanogaster CG12391 (13% identical), Drosophila melanogaster hb (11% identical), zebrafish plagl2 (10% identical), Caenorhabditis elegans hbl-1 (9% identical), zebrafish ovol1a (9% identical), zebrafish ovol1b (8% identical), Caenorhabditis elegans Y5F2A.4 (8% identical), zebrafish plagx (6% identical), Caenorhabditis elegans lin-48 (6% identical). Paralogues in human: ZSCAN18 (28% identical), ZNF202 (28% identical), ZNF274 (27% identical), ZNF446 (27% identical), ZSCAN32 (26% identical), ZSCAN29 (26% identical), ZKSCAN2 (24% identical), ZNF18 (24% identical), ZNF496 (23% identical), ZNF444 (22% identical), ZSCAN5C (21% identical), ZNF174 (21% identical), and 17 more.
Diseases named in the same sentence as ZSCAN1 in open-access papers:
ZSCAN1 is named in the same sentence as 15 diseases in open-access papers, as found by Europe PMC text mining. Sharing a sentence is not in itself a finding about the gene and the disease. The quoted sentences say what the papers report.
autonomic dysregulation (3 papers, 2024 to 2026). "Rapid-onset obesity with hypothalamic dysfunction, hypoventilation and autonomic dysregulation (ROHHAD) is a rare and often fatal pediatric neuroendocrine syndrome with strong evidence of antigen-driven paraneoplastic autoimmunity, including association with the intracellular autoantigen ZSCAN1." (PMID 42182119, 2026).
ROHHAD syndrome (3 papers, 2022 to 2024). "We used a comprehensive protein array analysis to identify candidate molecules in the sera of patients with ROHHAD syndrome and identified ZSCAN1 as a target antigen." (PMID 38339072, 2024). "In this cohort, 12 of the 14 patients (85.7%) with ROHHAD syndrome were positive for anti-ZSCAN1 autoantibodies." (PMID 38339072, 2024). "We also found that ZSCAN1 was co-expressed at the site of antibody reactivity to the IgG in the patient serum observed in mouse SFOs and an enzyme-linked immunosorbent assay showed that >85% of the patients with ROHHAD syndrome were positive for anti-ZSCAN1 autoantibodies." (PMID 38339072, 2024). "In the present study, 12 of the 14 patients were positive for anti-ZSCAN1 autoantibodies; however, the underlying pathology was unclear in the remaining two patients with ROHHAD syndrome who were negative for anti-ZSCAN1 autoantibodies." (PMID 38339072, 2024). "On the other hand, the relationship between ROHHAD syndrome in patients without tumors and the presence of anti-ZSCAN1 autoantibodies has not been elucidated." (PMID 38339072, 2024). "We identified ZSCAN1 as an autoantigen in patients with ROHHAD syndrome without tumors via protein array analysis and demonstrated that ZSCAN1 was co-expressed in the SFOs in mice by means of immunostaining using patient serum samples." (PMID 38339072, 2024). "Using a quantitative custom-made ELISA for the detection of anti-ZSCAN1 autoantibodies, we found that over 85% of the patients with ROHHAD syndrome without an NET exhibited a positive response to the anti-ZSCAN1 autoantibodies compared with that of the normal subjects." (PMID 38339072, 2024). "One is the identification of a novel antigen called ZSCAN1 in ROHHAD cases with tumors, cases in which ROHHAD-like symptoms were observed after COVID-19 infection, and cases including adults with anti-Nax and anti-SFO antibody responses in adipsic hypernatremia and ROHHAD syndrome." (PMID 35805903, 2022).
autoimmune disorders (2 papers, 2024 to 2026). "On the other hand, the normal subjects and those with autoimmune disorders were negative for anti-ZSCAN1 autoantibodies." (PMID 38339072, 2024).
neuroendocrine tumor (2 papers, 2024 to 2025). "ZSCAN1 was expressed in the hypothalamus and by the neuroendocrine tumor of one patient." (PMID 40775360, 2025).
breast carcinoma (1 paper, 2023). "Our finding thus improved our understanding of stemness regulation in BCSCs and suggests a therapeutic strategy for breast cancer caused by ZSCAN1 suppression." (PMID 36923432, 2023). "We thus also explored the mechanism underlying ZSCAN1 suppressing the proliferation of breast cancer cells." (PMID 36923432, 2023). "In this study, we found that ZSCAN1 is a novel tumor suppressor, which is suppressed in breast cancer cells and predicts a better prognosis of breast cancer patients; its suppression increased the tumorigenicity and stemness properties of breast cancer cells." (PMID 36923432, 2023).
cervical intraepithelial neoplasia (1 paper, 2021). "In a study identifying DNA methylation markers for the detection of high‐grade cervical intraepithelial neoplasia, the SOX1/ZSCAN1 panel (84%, 167/200) had a higher sensitivity and specificity compared to the others." (PMID 34056873, 2021).
lymphangioma (1 paper, 2024). A benign lesion composed of dilated lymphatic channels. "In our samples for the protein array, one case did not display the presence of anti-ZSCAN1 antibodies, in spite of a lymphangioma association." (PMID 38339072, 2024).
neural tumors (1 paper, 2023). "The recent identification of a specific autoantigen in ROHHAD patients with neural tumors and “active” disease—with positive ZSCAN1 autoantibodies both in peripheral blood and CSF, and ZSCAN1 expression in neural tumor tissues—supports the autoimmune-paraneoplastic hypothesis." (PMID 37609037, 2023).
tumor (6 papers, 2021 to 2025). "The tumor-initiating capacity of ZSCAN1-overexpressing BCSLCs was also significantly decreased versus control BCSLCs (3 replicates, P < 0.001 in MCF-7), as identified by an in vivo limiting dilution assay." (PMID 36923432, 2023). "In this investigation, we identified ZSCAN1 as a new tumor suppressor and transcriptional repressor that blocks TAZ’s ability to promote BC stemness." (PMID 36923432, 2023). "In summary, our findings revealed an important mechanism for BCSC maintenance: ZSCAN1, a novel tumor suppressor and transcriptional repressor, inhibits BCSC stemness via TAZ suppression." (PMID 36923432, 2023). "In addition, anti-ZSCAN1 auto-antibodies were present in serum of patients with ROHHAD who did not develop a tumor and absent in control samples in two additional studies." (PMID 40775360, 2025). "More recently, the presence of anti-Zinc finger and SCAN domain containing 1 (ZSCAN1) antibodies has been reported in ROHHAD, both in patients with NETs and in patients without tumours." (PMID 39595809, 2024).
cancer (1 paper, 2023). A tumor composed of atypical neoplastic, often pleomorphic cells that invade other tissues. "Taken together, these results support that ZSCAN1 is suppressed in BC cancer cells, associated with good prognosis, and ectopic expression of ZSCAN1 inhibits the proliferation of BC cells." (PMID 36923432, 2023). "Evidence has recently shown abnormal methylation and expression of ZSCAN1 in cancer tissues, but the critical role of this dysregulation is unknown." (PMID 36923432, 2023).
ZSCAN1 also shares sentences with these, for which no sentence is quoted: Obesity (3 papers); cervical cancer (1); ganglioneuroblastoma (1); ganglioneuroma (1); neuroblastoma (1).